VPS13B (vacuolar protein sorting 13 homolog B)
Description:
Mediates the transfer of lipids between membranes at organelle contact sites (By similarity). Binds phosphatidylinositol 3-phosphate (By similarity). Functions as a tethering factor in the slow endocytic recycling pathway, to assist traffic between early and recycling endosomes. Involved in the transport of proacrosomal vesicles to the nuclear dense lamina (NDL) during spermatid development (By similarity). Plays a role in the assembly of the Golgi apparatus, possibly by mediating trafficking to the Golgi membrane. Plays a role in the development of the nervous system, and may be required for neuron projection development. May also play a role during adipose tissue development. Required for maintenance of the ocular lens (By similarity).
Synonyms: CHS1; COH1; BLTP5B
Tractability: Antibody: UniProt places it where antibodies can reach, with high confidence. PROTAC: ubiquitination databases record sites on it; its protein half-life has been measured.
Gene: Protein-coding gene on chromosome 8 (99,013,266 to 99,877,580, forward strand). Ensembl gene ENSG00000132549.
Subcellular location: Recycling endosome membrane; Cytoplasmic vesicle, secretory vesicle, acrosome membrane; Golgi apparatus, cis-Golgi network membrane; Endoplasmic reticulum- Golgi intermediate compartment membrane; Golgi apparatus, trans-Golgi network membrane; Early endosome membrane; Lysosome membrane
Subcellular location (Human Protein Atlas): Cell Junctions
Gene Ontology:
Molecular function: phosphatidylinositol-3-phosphate binding
Biological process: adipose tissue development; Golgi organization; nervous system development; slow endocytic recycling; vesicle-mediated transport; acrosome assembly; central nervous system development; maintenance of lens transparency; neuron projection development
Cellular component: early endosome membrane; endoplasmic reticulum-Golgi intermediate compartment membrane; Golgi membrane; lysosomal membrane; acrosomal membrane; recycling endosome membrane; Golgi apparatus
Genetic constraint (gnomAD): Loss-of-function variants: 279 observed, 435.25 expected, observed/expected ratio (o/e) 0.64, 90% interval 0.58 to 0.71. The upper end of that interval is the gene's LOEUF score, 0.71, which puts it in group 2 of 6, group 1 being the genes least tolerant of losing a copy. Missense variants: 4,519 observed, 4,996 expected, observed/expected ratio (o/e) 0.9, 90% interval 0.88 to 0.93. Synonymous variants: 1,670 observed, 1,761.6 expected, observed/expected ratio (o/e) 0.95, 90% interval 0.91 to 0.99.
Gene-disease validity (ClinGen):
ClinGen rates the evidence that VPS13B causes each of these diseases.
Cohen syndrome (autosomal recessive): Definitive. Cohen syndrome (CS) is a rare genetic developmental disorder characterized by microcephaly, characteristic facial features, hypotonia, non-progressive intellectual deficit, myopia and retinal dystrophy, neutropenia and truncal obesity.
Homologues: Orthologues: macaque VPS13B (97% identical), pig VPS13B (91% identical), dog VPS13B (90% identical), rabbit VPS13B (90% identical), guinea pig VPS13B (90% identical), mouse Vps13b (87% identical), rat Vps13b (87% identical), tropical clawed frog vps13b (73% identical), chimpanzee VPS13B (21% identical).
Diseases named in the same sentence as VPS13B in open-access papers:
VPS13B is named in the same sentence as 88 diseases in open-access papers, as found by Europe PMC text mining. Sharing a sentence is not in itself a finding about the gene and the disease. The quoted sentences say what the papers report.
Cohen syndrome (69 papers, 2011 to 2026). "Cohen Syndrome (CS) is a rare neurodevelopmental disorder caused by mutations in VPS13B gene and affecting approximately 50,000 individuals worldwide." (PMID 41522673, 2026). "Cohen syndrome (CS) is a rare autosomal recessive neurodevelopmental disorder caused by biallelic variants in VPS13B, with an estimated prevalence of ~50,000 affected individuals worldwide." (PMID 41522673, 2026). "In this study, we investigated how loss of the vacuolar protein-sorting gene Vps13b, whose mutations cause human Cohen syndrome, affects brain development and behavior." (PMID 41522673, 2026). "Bi-allelic variants in the related gene VPS13B cause Cohen syndrome, a complex neurodevelopmental disorder characterized mainly by intellectual disability, hypotonia and progressive retinal dystrophy." (PMID 41522673, 2026). "Cohen syndrome is an autosomal recessive genetic disease caused by mutations in the vacuolar protein sorting homolog B (VPS13B) gene that leads to a variety of complications including periodontitis." (PMID 41730960, 2026). "Using this hANOs protocol, we investigated microcephaly phenotypes associated with Cohen syndrome (CS), which is caused by biallelic loss-of-function variants in the VPS13B gene." (PMID 41522673, 2026). "Biallelic pathogenic variants in VPS13B cause Cohen syndrome, which is characterized by severe myopia and progressive retinal dystrophy." (PMID 41153400, 2025). "Pathogenic variants in VPS13B have been reported in patients with Cohen syndrome, a rare autosomal recessive disease characterized by intellectual disability, dysmorphism, and microcephaly." (PMID 38572415, 2024). "Cohen Syndrome (CS) is a rare autosomal recessive disorder caused by biallelic mutations in the VPS13B gene." (PMID 39010945, 2024). "Mutations in VPS13B, a member of a protein family implicated in bulk lipid transport between adjacent membranes, cause Cohen syndrome." (PMID 38187698, 2023). "While it is well established that loss-of-function mutations in VPS13B cause Cohen syndrome, the contribution of missense variants to the pathomechanism remains unexplained." (PMID 37928888, 2023). "Cohen syndrome (CS) is a rare multisystem autosomal recessive disorder associated with mutations in VPS13B (vacuolar protein sorting homolog 13B)." (PMID 36780047, 2023). "Genetic variants in VPS13B have been identified to cause Cohen syndrome, but have been also linked to autism, retinal diseases, primary immunodeficiency, and short stature." (PMID 37928888, 2023). "Cohen Syndrome (CS) is a rare autosomal recessive disorder caused by biallelic loss-of-function mutations in the VPS13B gene." (PMID 37928888, 2023). "Biallelic pathogenic variants from the mother and father caused Cohen syndrome due to biallelic VPS13B pathogenic variants in trans configuration (c.5809_5810del and exon 32 deletion)." (PMID 38129582, 2023). "Pathogenic variants in vacuolar protein sorting 13 homolog B (VPS13B) cause Cohen syndrome (CS), a clinically diverse neurodevelopmental disorder." (PMID 37090188, 2023). "Five patients carried monoallelic P/LP variants in VPS13B, mapping within the Cohen syndrome critical region on 8q22, that manifest as a recessive disorder." (PMID 36035117, 2022). "While it is well established that loss-of-function mutations of VPS13B cause Cohen syndrome, the relevance of missense variants for the pathomechanism remains unexplained." (PMID 35690661, 2022). "Here we assessed the relevance of rare VPS13B missense variants for the development of Cohen syndrome." (PMID 35690661, 2022). "It is important to note that 5 VPS13B LP variants were detected in patients with a clear diagnosis of Cohen syndrome and in 1 patient with autism." (PMID 35690661, 2022). "Mutations in VPS13B are causally associated with Cohen syndrome (MIM# 216550), which is an autosomal recessive disorder characterized by microcephaly, facial dysmorphism, hypotonia, intellectual disability, and intermittent neutropenia." (PMID 36153334, 2022).
Cohen syndrome (continued). "Cohen syndrome is caused by a mutation of the vacuolar protein sorting 13 homolog B (VPS13B) gene on chromosome 8q22.2." (PMID 36232301, 2022). "An improved understanding of VPS13B missense variants in Cohen syndrome and the affected cellular processes are essential to provide mechanistic explanations and will help to elucidate the disease pathomechanisms." (PMID 35690661, 2022). "No genotype–phenotype correlations can currently be performed for Cohen syndrome or VPS13B-associated autism." (PMID 35690661, 2022). "Genetic variants in VPS13B have been found to cause Cohen syndrome, but have also been linked to autism, retinal disease, primary immunodeficiency, and short stature." (PMID 35690661, 2022). "Altogether, our study provides first in vitro evidence that rare VPS13B missense variants play a critical role for the pathogenesis of Cohen syndrome." (PMID 35690661, 2022). "All VPS13B missense variants of this study with a functional impact on Golgi integrity were identified in patients with a definite diagnosis of Cohen syndrome." (PMID 35690661, 2022). "While Cohen syndrome is majorly caused by VPS13B loss-of-function mutation, a rare number of missense variants has been published to cause Cohen syndrome." (PMID 35690661, 2022). "VPS13B-deficiency has been shown to fragment Golgi cisternae in fibroblasts derived from Cohen syndrome patients and in VPS13B-siRNA knockdown experiments." (PMID 35690661, 2022). "Genetic defects in VPS13B lead to the neurodevelopmental Cohen syndrome and were also linked to autism, intellectual disability, retinal disease, primary immunodeficiency disease, and short stature." (PMID 35690661, 2022). "Autosomal recessive VPS13B variants cause Cohen syndrome, characterized by obesity, hypotonia, mental deficiency, and facial, oral, ocular, and limb anomalies." (PMID 35870028, 2022). "The selection on VPS13B-associated missense variants for in vitro studies was based on a clear Cohen syndrome/autism association, family-based validation of the genetic finding, and low MAF." (PMID 35690661, 2022). "Mutations in VPS13B (COH1) are known to cause Cohen syndrome, a developmental disorder with intellectual disability and distinct craniofacial abnormalities." (PMID 34046249, 2021). "Here, we introduce a novel homozygous nonsense mutation (c.8698G > T, p.E2900X) in the VPS13B gene in an 11-year-old Iranian boy with major symptoms of Cohen syndrome." (PMID 34484844, 2021). "In a 41-year-old woman showing macula-dominant diffuse retinal dystrophy with mental retardation, Cohen syndrome caused by VPS13B was diagnosed." (PMID 33946315, 2021). "A few years later, VPS13B mutations were reported to cause Cohen syndrome, a rare neurodevelopmental condition." (PMID 34216812, 2021). "We have introduced mutations in the yeast VPS13 based on alleles found in chorea-acanthocytosis (VPS13A), Cohen syndrome (VPS13B), FTLD (VPS13C), and cerebellar ataxia (VPS13D) patients." (PMID 34046249, 2021). "The heterozygous mutation pattern seen in the vacuolar protein sorting 13 homolog B (VPS13B) gene is a pathogenic variant of Cohen syndrome." (PMID 34840762, 2021). "We reported a novel homozygous frameshift variant in VPS13B (LRG_351t1: c.7095del; p.Ser2366AlafsTer49) in a 4-year-old girl with Cohen syndrome." (PMID 32605629, 2020). "Cohen syndrome (CS) is an uncommon autosomal recessive developmental disorder that has been attributed to mutations in the VPS13B gene in patients of diverse genetic backgrounds." (PMID 32560273, 2020). "Missense or nonsense mutations in the Vacuolar protein sorting 13 homolog B (VPS13B) gene are the cause for Cohen syndrome with more than 150 known variants reported in The Human Gene Mutation Database." (PMID 32605629, 2020).
Cohen syndrome (continued). "In two young brothers referred with syndromic RD and with a history of neonatal hypotonia, microcephaly, and facial dysmorphism, the identification of biallelic pathogenic variants in the VPS13B (MIM *216550) allowed a final diagnosis of Cohen syndrome." (PMID 31736247, 2020). "Cohen syndrome (CS), a rare autosomal recessive disorder, has been associated with genetic mutations in the VPS13B gene, which regulates vesicle-mediated protein sorting and transport." (PMID 32560273, 2020). "Proband 12,651.p1, with an IQ of 34, carried pathogenic/likely pathogenic compound heterozygous variants (c.8185G > A, p.G2729R; c.2889G > A, p.W963X) in VPS13B, and was previously confirmed to have Cohen syndrome." (PMID 33023636, 2020). "Mutations in VPS13B have been associated with Cohen syndrome, a rare autosomal recessive neurodevelopmental disorder, and recessive variants have been reported in cases of ASD or ID with autistic features." (PMID 32081867, 2020). "NANS and GNE are genetic defects in the sialic acid biosynthesis pathway, and Cohen syndrome patients have a mutation in VPS13B, a protein important for proper GA function." (PMID 29497882, 2018). "Cohen syndrome is caused by an autosomal recessive (AR) mutation of the vacuolar protein sorting 13 homolog B (VPS13B, also referred to as COH1) gene on chromosome 8q22.2." (PMID 30473963, 2018). "VPS13B (vacuolar protein sorting 13, yeast, homologue of B) gene is the only gene responsible for Cohen Syndrome, causative mutations include nonsense, missense, indel and splice-site variants." (PMID 29149870, 2017). "As proof of principle, we apply the proposed methods to VPS13B, a gene mutated in the rare neurodevelopmental disorder called Cohen syndrome, and recently reported with recessive variants in autism." (PMID 25502226, 2014). "Our findings extend the mutational landscape of VPS13B in Cohen syndrome and autism and further strengthen the connection between Golgi homeostasis and autism." (PMID 25502226, 2014). "A 2‐year‐old girl with a confirmed diagnosis of Cohen syndrome caused by a homozygous c.8827C>T (p.Arg2943Ter) pathogenic variant in the VPS13B gene presented with global developmental delay, hypotonia, and speech delay, alongside significant findings of neutropenia and retinal dystrophy." (PMID 41466769, 2026). "The availability of molecular genetic testing has critically influenced the approach to diagnosing rare and ultrarare conditions such as VPS13A disease and XK disease (previously known as chorea-acanthocytosis and McLeod syndrome, respectively) as well as Cohen syndrome (due to VPS13B mutations)." (PMID 41522673, 2026). "Together, these findings identify VPS13B as a regulator of lysosomal homeostasis and provide insight into how VPS13B deficiency may contribute to Cohen syndrome pathology." (PMID 42104376, 2026). "The dysregulation of protein trafficking arising from VPS13B variants is hypothesized to contribute to axial elongation and the development of high myopia in patients with Cohen syndrome." (PMID 41153400, 2025). "Cohen syndrome is an autosomal recessive disorder caused by VPS13B (COH1) gene mutations." (PMID 38067130, 2023). "The loss of functional VPS13B is pathogenic for Cohen syndrome pathology, a rare autosomal multisystem disorder principally characterized by physiological defects, a distorted perception of self, intellectual disability, and intermittent congenital neutropenia." (PMID 36404287, 2023). "Of note, the Stereotyped Behaviors and Restricted Interests total score in Autism Diagnostic Observation Schedule Module 3 was significantly associated with multiple variants in the VPS13B gene, a causal gene for Cohen syndrome and a candidate gene for syndromic ASD." (PMID 36153334, 2022). "Interestingly, the common genetic variants in the VPS13B gene—a disease-causing gene for Cohen syndrome—were associated with a core symptom of ASD." (PMID 36153334, 2022).
Cohen syndrome (continued). "Although the vast majority of VPS13B variants are protein length changing, 29 missense variants are reported in association with clinical conditions such as Cohen syndrome, autism, intellectual disability, retinal disease, primary immunodeficiency disease, and/or short stature." (PMID 35690661, 2022). "Notably, a causal gene for syndromic ASD—VPS13B and Cohen syndrome—that was previously discovered by a family study was associated with the severity of a core ASD symptom." (PMID 36153334, 2022). "Thus the two VPS13B variants, that were inherited from the two heterozygous parents, were considered as causative of the Cohen Syndrome in this patient." (PMID 36035117, 2022). "Recessive loss-of-function mutations in the gene encoding VPS13B are responsible for Cohen syndrome (hence the alias COH1), a neurodevelopmental condition characterized by heterogeneous manifestations including microcephaly, intellectual disabilities and hypotonia." (PMID 34216812, 2021). "Cohen syndrome (CS) is a rare genetic disorder caused by variations affecting the VPS13B gene." (PMID 34046249, 2021). "Meanwhile, retinal dystrophy is a major symptom of Cohen syndrome caused by VPS13B mutations in the VPS13 family, and thus VPS13D mutations might cause the retinal symptom." (PMID 31876103, 2020). "To date, more than 150 mutations of VPS13B have been reported in over 200 Cohen syndrome patients." (PMID 32605629, 2020). "Finally, in a consanguineous Middle-Eastern patient (RP-1430) with RD and mental disability, a novel causative homozygous frameshift variant was found in the VPS13B gene, which is associated with Cohen syndrome." (PMID 29588463, 2018). "Cohen syndrome is caused by mutations in Vesicle Protein Sorting 13B (VPS13B)." (PMID 21605373, 2011). "One gene of note in this region is VPS13B, which may have an important role in development and is associated with Cohen syndrome, which has an effect on development of many parts of the body." (PMID 22022279, 2011). "Furthermore, multiple inward‐facing missense mutations were found within the hydrophobic interior of the RBG domain, one of which was pathogenic for Cohen syndrome in VPS13B (p.Ile1636Asn, VCV000977843.1), and another one was likely pathogenic in VPS13D (p.Ile1170Ser, VCV000806071.11)." (PMID 36404287, 2023). "Therefore, the LoF variants might prevent proper localization of VPS13B and disruption of its molecular functions on Golgi assembly or maintenance, triggering the pathological cascades underlying Cohen syndrome and/or autism." (PMID 25502226, 2014). "In conclusion, these preliminary findings provide new insights into the muscle biology of VPS13B and highlight a likely central contribution to the hypotonia observed in Cohen syndrome, which remains to be validated." (PMID 41522673, 2026). "To gain insights into the myopathogenesis of Cohen syndrome, we systematically reviewed the literature and identified 47 reports of VPS13B-related cases." (PMID 41522673, 2026). "Mutations in each of them cause severe neurological disorders: chorea-acanthocytosis (VPS13A), Cohen syndrome (VPS13B), Parkinson’s disease (VPS13C), and several neurological disorders or embryonic lethality in the case of complete loss-of-function (VPS13D)." (PMID 39331042, 2024). "In agreement with localization of VPS13B in the Golgi complex, a less compact Golgi structure and an altered N-glycosylation pattern were observed in cells from Cohen syndrome patients and in several mammalian VPS13B knock-out (KO) and knock-down cell lines." (PMID 39331042, 2024). "It has been reported that the mutations of VPS13A (OMIM *605978), VPS13B (OMIM *607817), and VPS13C (OMIM *608879) lead to chorea acanthocytosis (OMIM #200150), Cohen syndrome (OMIM #216550), and parkinsonism (OMIM #616840), respectively." (PMID 31876103, 2020). "The Cohen syndrome gene, VPS13B, is a potential transmembrane protein involved in vesicle-mediated transport and sorting within the cell." (PMID 21605373, 2011).